YPEL2 (yippee like 2)
Synonyms: FKSG4
Tractability: No criterion of Open Targets' tractability assessment is met for any kind of drug.
Gene: Protein-coding gene on chromosome 17 (59,331,655 to 59,401,729, forward strand). Ensembl gene ENSG00000175155.
Subcellular location: Nucleus, nucleolus
Gene Ontology:
Molecular function: protein binding
Cellular component: nucleolus
Genetic constraint (gnomAD): Loss-of-function variants: 2 observed, 16.95 expected, observed/expected ratio (o/e) 0.12, 90% interval 0.047 to 0.37. The upper end of that interval is the gene's LOEUF score, 0.37, which puts it in group 1 of 6, group 1 being the genes least tolerant of losing a copy. Missense variants: 64 observed, 141.2 expected, observed/expected ratio (o/e) 0.45, 90% interval 0.37 to 0.56. Synonymous variants: 51 observed, 51.56 expected, observed/expected ratio (o/e) 0.99, 90% interval 0.79 to 1.25.
Homologues: Orthologues: dog YPEL2 (100% identical), guinea pig YPEL2 (100% identical), macaque YPEL2 (100% identical), mouse Ypel2 (100% identical), pig YPEL2 (100% identical), rabbit YPEL2 (100% identical), rat Ypel2 (100% identical), tropical clawed frog ypel2 (100% identical), zebrafish ypel2b (97% identical), Drosophila melanogaster Ypel (83% identical). Paralogues in human: YPEL1 (97% identical), YPEL3 (89% identical), YPEL4 (81% identical), YPEL5 (37% identical), SARDH (32% identical), DMGDH (31% identical), AMT (24% identical), PDPR (23% identical), L2HGDH (18% identical), FOXRED1 (14% identical).
Diseases named in the same sentence as YPEL2 in open-access papers:
YPEL2 is named in the same sentence as 9 diseases in open-access papers, as found by Europe PMC text mining. Sharing a sentence is not in itself a finding about the gene and the disease. The quoted sentences say what the papers report.
atherosclerosis (1 paper, 2025). A disease characterized by the build-up of fatty material and calcium deposition in the arterial wall resulting in partial or complete occlusion of the arterial lumen. "circRNAs from HSPG2 and YPEL2 in blood PBMC samples detected atherosclerosis with an AUC of 0.73." (PMID 39901821, 2025). "A specific set of circRNAs was capable of distinguishing atherosclerotic from healthy arterial tissue in individual patients, and circRNAs from YPEL2 and HSPG2 served to distinguish patients with atherosclerosis from non-atherosclerosis individuals by blood sampling." (PMID 39901821, 2025).
breast carcinoma (1 paper, 2022). "High levels of Klhl24, Hbp1, Crebrf, Ypel2, CD22 and Ypel3 were correlated with better outcomes, whereas lower levels of Gdf15, Cdc25a, Ddit4 and Psat1 were associated with better prognosis in breast cancer patients." (PMID 34990474, 2022).
COVID-19 (1 paper, 2022). A disease caused by infection with severe acute respiratory syndrome coronavirus 2. "In the present study, four risk regulators (UBTF, POLR2L, YBX1 and YPEL2) were identified to be associated with COVID-19 severity." (PMID 35139909, 2022). "Furthermore, four risk genes (upstream binding transcription factor, RNA polymerase II, I and III subunit L, Y-box binding protein 1 and yippee like 2) were found to be associated with COVID-19 severity." (PMID 35139909, 2022).
dry eye (1 paper, 2021). "Moreover, based on our current database of RNA-seq, our results suggested that other oxidative-related genes, such as YPEL2 and HSPA2 could become promising treatment targets in dry eye after systematic in vitro and in vivo studies." (PMID 35096875, 2021).
Hypertension (1 paper, 2023). The presence of chronic increased pressure in the systemic arterial system. "Amongst the 9 novel lipid-associated loci, the PheWAS revealed that the cluster 11 associated intronic variant rs149807191 at the YPEL2 locus associated also with hypertension endpoints (minimum P = 2e-7)." (PMID 37907536, 2023).
type 2 diabetes (1 paper, 2024). "Additionally, miR-200 (in particular miR-200c) has been shown overexpressed in pancreatic islets in diabetic mice and lead to ß-cell apoptosis through a Zeb1 independent pathway and possibly through Ypel2, a potential oncogene, leading to type 2 diabetes." (PMID 38978141, 2024).
cancer (2 papers, 2006 to 2019). A tumor composed of atypical neoplastic, often pleomorphic cells that invade other tissues. "The results showed that these hub genes exhibited distinct expression patterns in different cancers, such as RNF8 in THYM, YPEL2 in LAML and E2F6 in DLBC, which indicated the potential relation of these genes with the corresponding cancer." (PMID 31709182, 2019). "A specific gene with highly differential expression, such as RNF8 in THYM, YPEL2 in LAML, and E2F6 in DLBC, indicates a strong correlation between this gene and the corresponding cancer." (PMID 31709182, 2019). "Upregulation in cancers was seen in TWISTNB 4, YPEL2 3, CBX3 3, SOX9 8 and β-catenin 7, while downregulation was seen in TWISTNB 6, YPEL2 1, YPEL5 3, SEPT4 2, SEPT6 4, CBX3 3, SOX9 2 and β-catenin 2, compared with those in normal mucosa." (PMID 16504081, 2006).
YPEL2 also shares sentences with these, for which no sentence is quoted: breast tumor (1 paper); retinitis pigmentosa (1).